NOL4 (nucleolar protein 4)
Synonyms: NOLP; HRIHFB2255; CT125
Tractability: PROTAC: its protein half-life has been measured.
Gene: Protein-coding gene on chromosome 18 (33,851,100 to 34,224,952, reverse strand). Ensembl gene ENSG00000101746.
Subcellular location: Nucleus, nucleolus
Subcellular location (Human Protein Atlas): Nucleoplasm
Gene Ontology:
Molecular function: RNA binding
Cellular component: nucleoplasm; nucleolus
Genetic constraint (gnomAD): Loss-of-function variants: 11 observed, 55.92 expected, observed/expected ratio (o/e) 0.2, 90% interval 0.12 to 0.33. The upper end of that interval is the gene's LOEUF score, 0.33, which puts it in group 1 of 6, group 1 being the genes least tolerant of losing a copy. Missense variants: 552 observed, 719.7 expected, observed/expected ratio (o/e) 0.77, 90% interval 0.71 to 0.82. Synonymous variants: 258 observed, 266.23 expected, observed/expected ratio (o/e) 0.97, 90% interval 0.88 to 1.07.
Homologues: Orthologues: chimpanzee NOL4 (100% identical), macaque NOL4 (99% identical), rabbit NOL4 (98% identical), pig NOL4 (97% identical), dog NOL4 (97% identical), guinea pig NOL4 (97% identical), mouse Nol4 (95% identical), rat Nol4 (94% identical), tropical clawed frog nol4 (83% identical). Paralogues in human: NOL4L (58% identical).
Diseases named in the same sentence as NOL4 in open-access papers:
NOL4 is named in the same sentence as 20 diseases in open-access papers, as found by Europe PMC text mining. Sharing a sentence is not in itself a finding about the gene and the disease. The quoted sentences say what the papers report.
cervical cancer (4 papers, 2014 to 2021). A primary or metastatic malignant neoplasm involving the cervix. "Aberrant methylation of CpG islands in the NOL4 gene promoter has been reported to be associated with 85% of the cervical cancer patients and 91% of head and neck squamous cell carcinoma (HNSCC)." (PMID 33415070, 2020). "NOL4 (nucleolar protein 4) is a novel methylation target in cervical cancer, and has been suggested as an early detection and risk prediction biomarker in cervical cancer." (PMID 32074080, 2020). "NOL4, known as nucleolar protein 4, was identified a novel methylated tumor suppressor gene in head and neck cancer and cervical cancer." (PMID 34065612, 2021).
prostate carcinoma (4 papers, 2013 to 2021). A carcinoma that arises from epithelial cells of the prostate gland. "An increased expression of NOL4 has been reported in prostate cancer patients and was reported to be significantly associated with the aggressiveness of the disease." (PMID 33415070, 2020). "Additionally, NOL4 gene is a biomarker candidate of many CT antigens for diagnosis and prognosis of prostate cancer and is a new potential therapeutic target in glioblastoma stem cells." (PMID 34065612, 2021). "Finally, it has been demonstrated that NEFM was diffusely expressed in prostate cancer cells undergoing neuronal trans-differentiation and NOL4 was described as a biomarker for aggressiveness prostate cancer." (PMID 32041153, 2020).
glioblastoma (3 papers, 2017 to 2025). The most malignant astrocytic tumor (WHO grade IV). "Furthermore, NOL4 was recently shown to be one of the 20 aberrantly expressed genes in the most common and the most lethal primary brain tumor, glioblastoma (GBM)." (PMID 28362316, 2017). "Finally, NOL4 and IGF2BP2 are instead directly involved in the maintenance of Glioblastoma Stem Cells." (PMID 40507925, 2025). "Ultimately, two of these genes have a direct role in Glioblastoma Stem Cells: NOL4 (nucleolar protein 4) was identified as 1 of 20 genes expressed in GSCs but not in NSCs and, for this, as new possible therapeutic target." (PMID 40507925, 2025).
head and neck squamous cell carcinoma (3 papers, 2014 to 2020). A squamous cell carcinoma that arises from any of the following anatomic sites: lip and oral cavity, nasal cavity, paranasal sinuses, pharynx, larynx, and salivary glands. "For example, aberrant methylation of CpG islands in the NOL4 gene promoter was shown to be associated with cervical and head and neck squamous cell carcinoma (HNSCC)." (PMID 28362316, 2017).
breast carcinoma (2 papers, 2021 to 2024). "We identified seven potential genes within breast cancer: NOL4, STAR, C8G, NEIL1, SLC46A3, FRMD6, and SCARF2." (PMID 39199284, 2024). "In addition, NOL4 mRNA was expressed weakly, detected at a low frequency, or not detected, in non-small-cell lung cancer, ovarian cancer, breast cancer, mesothelioma, colon cancer, melanoma, and hepatocellular carcinoma." (PMID 34065612, 2021). "Through differential expression analysis and mutual information, we identified seven genes (NOL4, STAR, C8G, NEIL1, SLC46A3, FRMD6, and SCARF2) that are potential biomarkers in breast cancer." (PMID 39199284, 2024).
glioma (2 papers, 2018 to 2020). A benign or malignant brain and spinal cord tumor that arises from glial cells (astrocytes, oligodendrocytes, ependymal cells). "Most of the CSF samples procured from GBM patients showed the presence of TA autoantibodies against NOL4 and KALRN while low grade glioma samples showed an antigenic response against UTP4 and CCDC28A." (PMID 33415070, 2020). "Proteins NOL4 (a cancer-testis antigen) and KALRN showed an antigenic response in the CSF of GBM patients, whereas, UTP4 and CCDC28A showed an antigenic response in low grade gliomas when compared with the control samples." (PMID 33415070, 2020). "Although no information is available for the role of NOL4 in cancer, TMEM97 has been shown to be upregulated in several malignancies, including glioma as well as colorectal and ovarian cancers." (PMID 29599847, 2018).
small cell lung carcinoma (2 papers, 2021). Small cell lung cancer (SCLC) is a highly aggressive malignant neoplasm, accounting for 10-15% of lung cancer cases, characterized byrapid growth, and early metastasis. "The protein encoded by Nol4 is associated with RNA binding and has been identified as a cancer/testis antigen in humans, recently presented as a candidate target in small cell lung cancer." (PMID 34868271, 2021). "RT-PCR and western blot analysis showed that NOL4 was frequently present in small-cell lung cancer cell lines (8/9, 8/9)." (PMID 34065612, 2021). "A humoral response against NOL4 proteins was detected in 75% (33/44) of small-cell lung cancer patients and in 65% (13/20) of healthy donors by a serological western blot assay." (PMID 34065612, 2021). "Our results reveal that NOL4 was expressed at protein levels in small-cell lung cancer tissues (10/10) but not detected in lung adenocarcinoma and squamous cell carcinoma by immunohistochemical analysis." (PMID 34065612, 2021).
lung adenocarcinoma (1 paper, 2021). A carcinoma that arises from the lung and is characterized by the presence of malignant glandular epithelial cells. "NOL4 was expressed at protein levels in 10/10 of SCLC tissue specimen but not detected in lung adenocarcinoma and squamous cell carcinoma." (PMID 34065612, 2021).
mesenchymal tumors (1 paper, 2015). "NOL4 and RAPGEF4 (cluster III) were highly expressed in proneural and weakly expressed in mesenchymal tumors." (PMID 26295306, 2015).
cancer (11 papers, 2014 to 2025). A tumor composed of atypical neoplastic, often pleomorphic cells that invade other tissues. "Nucleolar protein 4 (NOL4), implicated in DNA repair, cell proliferation and metastasis, has emerged as a potential target for cancer immunotherapy ⁠." (PMID 40068812, 2025). "NOL4 (Nucleolar Protein 4) is involved in ribosome biogenesis and RNA processing and is up-regulated in various cancers, also promoting tumor progression." (PMID 39199284, 2024). "For the application of the NOL4 in immunotherapy and cancer diagnosis, more detailed studies such as epitopes purification, antibody synthesis, and immunohistochemical analysis are required." (PMID 34065612, 2021). "Meanwhile, NOL4, PAX6, TRIM58, and ZNF382 promoter methylation was also associated with the occurrence of many cancers." (PMID 31956659, 2019). "Curiously, two other highly disordered CTAs, NOL4 and CEP55, were shown to be associated with different types of cancer." (PMID 28362316, 2017). "After validation with QMSP, one gene, NOL4, was highly methylated (91%) in tumor samples and unmethylated in normal salivary rinses and minimally methylated in normal mucosal samples demonstrating cancer-specific methylation in HNSCC tissues." (PMID 24337411, 2014). "Following the confirmation of EMT in EC, TTK, LY6K, and NOL4 have recently been reported as cancer-testis antigens with a bad prognosis, with TTK being particularly overexpressed in early-stage cancer." (PMID 41312167, 2025). "Like NOL4, CEP55 is also known to be expressed in various cancers, being barely detectable in normal tissues except for testis and thymus." (PMID 28362316, 2017). "In addition, NOL4 mRNA was weakly, or at a low frequency, or not detected in various cancer cell lines." (PMID 34065612, 2021).
tumor (5 papers, 2014 to 2025). "We found more than one TA was expressed per tumor, and seven TAs (GPC3, IGF2BP3, NOL4, NR6A1, PKB, PRAME, and SPAG17) were detected in multiple tumors." (PMID 40894019, 2025).
NOL4 also shares sentences with these, for which no sentence is quoted: head and neck cancer (3 papers); colon cancer (1); hepatocellular carcinoma (1); melanoma (1); mesothelioma (1); non-small cell lung carcinoma (1); ovarian carcinoma (1); squamous cell carcinoma (1); viral infection (1).